SMOC2 (SPARC related modular calcium binding 2)
Diseases named in the same sentence as SMOC2 in open-access papers (continued):
Sharing a sentence is not in itself a finding about the gene and the disease.
colon cancer (3 papers, 2020 to 2022). "To further investigate the underlying mechanism of SMOC2-induced tumor suppressive effects in colon cancer cells, we performed cDNA microarray analysis using SMOC2-expressing stable cell lines." (PMID 32884102, 2020). "In vitro assays showed that SMOC2 over-expression suppressed proliferation and migration, as well as colony and sphere forming abilities in some colon cancer cell lines." (PMID 32884102, 2020). "This is consistent with the result of our migration assay, in which induced-SMOC2 over-expression led to decreased migratory activity of colon cancer cells, even though it was only observed in DLD1 cells among the two cell lines examined." (PMID 32884102, 2020). "In agreement with its prognostic effect, we discovered that SMOC2 overexpression in colon cancer cells resulted in significantly attenuated proliferation, migration, and colony forming abilities, suggesting a tumor suppressive role of SMOC2 in cancer progression." (PMID 32884102, 2020).
fibrosis (3 papers, 2020 to 2025). the formation of excess fibrous connective tissue in an organ or tissue in a reparative or reactive process. "Other proteins such as TSP-1, OPN, proteoglycans lumican and agrin, and matricellular proteins SPARC and SMOC2 have a clear association with fibrosis in NAFLD patients and animal models." (PMID 33262757, 2020). "In line with previous studies, we found that ILK was overactivated adaptively in sustained profibrogenic factors-induced mice fibrosis model to respond to the up-regulation of SMOC2." (PMID 36935650, 2022). "SMOC2 silencing alleviated cardiac fibrosis through inhibition of the ILK/p38 signaling." (PMID 40362577, 2025).
liver fibrosis (3 papers, 2022 to 2026). "Notably, SMOC2-knockout mice exhibited protection against liver fibrosis and reduced hepatic inflammation induced by HFD." (PMID 38565287, 2024). "In addition, it is known that ANGTPL2, also regulated by TGF-β, has an inflammatory and fibrogenic potential and that suppression of SMOC2 ameliorates kidney, pulmonary, and liver fibrosis." (PMID 35216219, 2022).
lymph node metastasis (3 papers, 2020 to 2022). "For PTCs with lymph node metastasis, we compared the levels of SMOC2 between primary PTCs and metastatic cancers." (PMID 32184420, 2020). "Next, we also performed immunohistochemistry for SMOC2 on a large cohort of PTCs (n = 338) including 122 PTCs with lymph node metastasis." (PMID 32184420, 2020). "It was notable that SMOC2 expression further decreased in lymph node metastasis (P = 0.002)." (PMID 32184420, 2020). "Furthermore, it is noteworthy to highlight that we found SMOC2 expression to be significantly reduced when cancer cells invaded into deeper layers and did not further decline during lymph node metastasis." (PMID 32884102, 2020).
pancreatic cancer (3 papers, 2020 to 2022). "Western blotting was used to detect the protein expression of SMOC2 in 30 pairs of pancreatic cancer tissue and corresponding paracancerous tissue samples." (PMID 34976169, 2022). "The results of in vivo and in vitro experiments in this study showed, for the first time, that SMOC2 expression was intimately correlated with the malignant progression of pancreatic cancer and that SMOC2 played a cancer-promoting effect." (PMID 34976169, 2022). "In this study, we aimed to confirm that hsa_circ_0074298 can promote the proliferation and metastasis of pancreatic cancer cells and to explore the regulatory effect of hsa_circ_0074298 on the miR-519d/SMOC2 axis." (PMID 34976169, 2022). "Our results showed that hsa_circ_0074298 sponged miR-519d and thus affected the downstream SMOC2 gene to promote pancreatic cancer progression and gemcitabine resistance." (PMID 34976169, 2022). "In summary, we identified the hsa_circ_0074298/miR-519d/SMOC2 regulatory axis in pancreatic cancer for the first time." (PMID 34976169, 2022). "The results showed that SMOC2 was highly expressed in pancreatic cancer tissue (P<0.001) and was negatively correlated with miR-519d expression." (PMID 34976169, 2022). "The results showed that in pancreatic tumor cells stably transduced with sh-circ0074298, transfection of miR-519d inhibitor or SMOC2 overexpression plasmids reversed the decrease in cell proliferation caused by the downregulation of hsa_circ_0074298 (P<0.001)." (PMID 34976169, 2022). "However, the mechanism by which SMOC2 exerts drug resistance in pancreatic cancer remains to be elucidated." (PMID 36238299, 2022).
adenoma (2 papers, 2018 to 2020). A neoplasm arising from the epithelium. "Thereby, we validated the downregulation of the stem cell markers Smoc2, Lgr5 and Olfm4, as well as the repression of several genes involved in the Wnt/β-catenin signaling and/or Notch signaling in Ap4-deficient adenomas." (PMID 30177706, 2018). "By directly comparing the H-scores of SMOC2 between adenoma and carcinoma areas that co-exist in the same tumor, we found that high levels of SMOC2 expression was persistent during the adenoma to carcinoma transition." (PMID 32884102, 2020). "In particular, we analyzed alterations in the expression of SMOC2 during CRC progression: adenoma-carcinoma transition, muscle layer invasion, and lymph node metastasis." (PMID 32884102, 2020). "It was extremely rare to see the case where SMOC2 expression is higher in carcinoma areas than in pre-existing adenoma areas." (PMID 32884102, 2020). "Up-regulated SMOC2 expression remained persistent during adenoma-carcinoma progression, however, it significantly decreased while invading the deeper layers." (PMID 32884102, 2020). "To determine differential SMOC2 expression over adenoma-carcinoma progression, we collected 24 cases of CRCs that co-exist with pre-existing adenomas." (PMID 32884102, 2020). "The deletion of Ap4 in these tumor organoids was accompanied by lower levels of the ISC markers Smoc2, Lgr5 and Olfm4 when compared with Ap4 wild-type adenomas." (PMID 30177706, 2018). "Interestingly, in hyperplastic polyps (HPs) and sessile serrated adenomas (SSAs), SMOC2 expression remained at the bottom of the crypts with weak to moderate stain intensity." (PMID 32884102, 2020). "Furthermore, while upregulated SMOC2 expression was maintained during the adenoma-carcinoma transition, it decreased in cancer cells at the invasive front but did not decline further during lymph node metastasis." (PMID 32884102, 2020). "Immunohistochemical analysis showed that SMOC2-positive cells were confined to the crypt bases in the normal intestinal mucosa, hyperplastic polyps, and sessile serrated adenomas, whereas traditional serrated adenomas and conventional adenomas exhibited focal or diffuse distribution patterns." (PMID 32884102, 2020).
chronic kidney disease (2 papers, 2022 to 2023). Impairment of the renal function secondary to chronic kidney damage persisting for three or more months. "On the other hand, SMOC2 plays a pro-fibrotic role in the mouse model of chronic kidney disease via autophagy activation, suggesting a potential association between SMOC2 and autophagy." (PMID 37465345, 2023).
dementia (2 papers, 2019 to 2025). Loss of intellectual abilities interfering with an individual's social and occupational functions. "Similarly, proteins such as MMP8, IL32, NDRG1, SMOC2, or ESM1, which have been previously reported to contribute to AD pathology, showed to be significantly increased in both MCI A + T + and AD dementia, but not in MCI A-T-, suggesting a specific AD-related signature in pEVs proteome." (PMID 41282153, 2025).
dentin dysplasia (2 papers, 2018 to 2023). Dentin dysplasia (DD) is a rare disorder belonging to the group of hereditary dentin defects and is characterized by abnormal dentin structure and root development resulting in abnormal tooth development. "In humans, pathogenic mutations in SMOC2 have been implicated in severe dental anomalies and skeletal dysplasia, characterized by microdontia, dentin dysplasia, reduced alveolar/jaw bone density, and flatten lumbar vertebrae." (PMID 37448626, 2023).
Hashimoto thyroiditis (2 papers, 2020 to 2024). An autoimmune disorder caused by the production of autoantibodies against thyroid tissue. "SMOC2 polymorphisms may also be associated with an increased risk for Hashimoto thyroiditis and Graves’ disease." (PMID 38668354, 2024). "NH showed similar levels of SMOC2 to the normal follicular cells, whereas SMOC2 expression was significantly lower in lymphocytic thyroiditis." (PMID 32184420, 2020). "SMOC2 expression was significantly lower in lymphocytic thyroiditis and in follicular tumors including FAs and carcinomas." (PMID 32184420, 2020). "However, SMOC2 expression was significantly lower in lymphocytic thyroiditis and follicular tumors including follicular adenomas and carcinomas." (PMID 32184420, 2020). "Interestingly, SMOC2 expression was significantly decreased in lymphocytic thyroiditis, whereas NH showed the same level of SMOC expression as normal thyroid follicles." (PMID 32184420, 2020). "Interestingly, when looking into 47 non-cancerous tissues, SMOC2 mRNA expression was significantly lower in lymphocytic thyroiditis than in nodular hyperplasia or normal thyroid tissues." (PMID 32184420, 2020).
Insulin resistance (2 papers, 2024 to 2025). Increased resistance towards insulin, that is, diminished effectiveness of insulin in reducing blood glucose levels. "Scavenger Receptor Class A Member 5 (SCARA5), TNFRSF12A, GDF-8, and Related Modular Calcium Binding 2 (SMOC2) were associated with insulin resistance markers and steatosis grade." (PMID 39407757, 2024). "Although only SMOC2 in SAT reached statistical significance, lower gene expression across all genes was observed in individuals with insulin resistance (IR; N = 42) compared to their insulin-sensitive (IS; N = 31) counterparts, with this pattern being more pronounced in OVAT." (PMID 41275133, 2025). "MSR1, KYNU, and RBKS, but not SMPD1, were associated with metabolic and liver dysfunction markers, while SCARA5, TNFRSF12A, SMOC2, but not GDF-8, were associated with insulin resistance markers." (PMID 39407757, 2024). "RBKS, but not SMPD1, was associated with metabolic and liver dysfunction markers, while SCARA5, TNFRSF12A, and SMOC2, but not GDF-8, were associated with insulin resistance markers, and steatosis grade in the OB group." (PMID 39407757, 2024).
myocardial ischemia (2 papers, 2020). A disorder of cardiac function caused by insufficient blood flow to the muscle tissue of the heart. "SMOC2 is differentially increased in failing human heart, potentially marking injury-induced myocardial ischemia and/or fibrosis." (PMID 32908163, 2020). "SMOC-2 is highly expressed during wound healing; it could stimulate endothelial cell proliferation and angiogenic activity, thus serving as a target for angiogenesis in myocardial ischemia." (PMID 32831862, 2020).
Obesity (2 papers, 2021 to 2025). Accumulation of substantial excess body fat. "In line with this, in a third cohort stratified by metabolic health status among individuals with obesity (MHO/MUO), DES, DSP, and SMOC2 again showed significantly higher gene expression in OVAT compared to SAT." (PMID 41275133, 2025). "In the current study, we validated the depot-specific gene expression of GJA1, DES, DSP, and SMOC2 in intra-individually paired SAT and OVAT samples from 78 individuals with obesity from our in-house cohort using quantitative PCR." (PMID 41275133, 2025). "Moreover, although non-significant, we observed the same effect direction for DES, DSP and SMOC2 among individuals without obesity (N = 31)." (PMID 41275133, 2025).
papillary thyroid carcinomas (2 papers, 2020 to 2024). "Its expression is downregulated in papillary thyroid carcinomas, and SMOC2 positivity is associated with a better prognosis." (PMID 38668354, 2024).
renal fibrosis (2 papers, 2025 to 2026). A final common manifestation of a wide variety of chronic kidney diseases characterized by glomerulosclerosis and tubulointerstitial fibrosis. "Although SMOC2 has been implicated in renal fibrosis through fibroblast activation, its role during AKI remains unknown." (PMID 41663805, 2026). "Furthermore, in an AAI-induced AKI-to-CKD model, SMOC2 deficiency exacerbated renal fibrosis, linking early tubular protection to long-term outcomes." (PMID 41663805, 2026). "Research has shown that in renal fibrosis, SMOC2 contributes to fibrogenesis by enhancing inflammatory responses and activating the MAPK, SMAD and AKT signalling pathways." (PMID 40913254, 2025).
anaplastic carcinoma (1 paper, 2020). "In this study, we thoroughly examined the expression profile of SMOC2 in various thyroid diseases even though some rare thyroid malignancies were not included such as medullary, poorly differentiated, and anaplastic carcinoma." (PMID 32184420, 2020).
aortic valve calcification (1 paper, 2022). "Among DEGs not related to humoral immunity many overlap with those already implicated in aortic valve calcification, these include TNC, PRG4, COL11A1, SMOC2, FN1, and OGN." (PMID 36437309, 2022).
asthma (1 paper, 2021). "We will construct a mouse model of asthma to further explore the functional role of SMOC2 in asthma in vivo." (PMID 34876240, 2021). "Although the function of SMOC2 is confirmed in several diseases, its role in asthma remains poorly understood." (PMID 34876240, 2021). "In this study, we aimed at investigating whether SMOC2 can participate in TGF-β1-induced proliferation, migration and FMT in lung fibroblasts and further to determine the involvement of SMOC2 in asthma." (PMID 34876240, 2021). "This article only explored the mechanism of action of SMOC2 in asthma through in vitro experiments." (PMID 34876240, 2021). "Taken together, SMOC2 influenced asthma progression via the activation of AKT and ERK pathways." (PMID 34876240, 2021). "The results highlight the role of SMOC2 in asthma, which might offer a promising target molecule for asthma treatment." (PMID 34876240, 2021). "Nonetheless, the exact role of SMOC2 in asthma is still largely unknown." (PMID 34876240, 2021). "In a word, our study found that SMOC2 participated in TGF-β1-induced proliferation, migration and FMT in lung fibroblasts, which might aggravate the progression of asthma." (PMID 34876240, 2021). "This work demonstrated that SMOC2 modulated TGF-β1-induced proliferation, migration and FMT in lung fibroblasts and may promote asthma, which attributed to activation of AKT and ERK pathways." (PMID 34876240, 2021). "We were curious about whether SMOC2 could affect AKT and ERK pathways in asthma, and thus we examined the expression of AKT and ERK pathway-related proteins through western blot analysis." (PMID 34876240, 2021). "The results of our study illustrated that SMOC2 was involved in TGF-β1-induced proliferation, migration and myofibroblast transformation in lung fibroblasts, which may contribute to asthma." (PMID 34876240, 2021). "This work demonstrated that SMOC2 modulated TGF-β1-induced proliferation, migration and FMT in lung fibroblasts and may promote asthma, which potentially provided a novel therapeutic target for the management of asthma." (PMID 34876240, 2021).
atherosclerosis (1 paper, 2018). A disease characterized by the build-up of fatty material and calcium deposition in the arterial wall resulting in partial or complete occlusion of the arterial lumen. "This suggests that SMOC2 could have a potential therapeutic benefit in diseases which involve vascular calcification such as atherosclerosis." (PMID 29897942, 2018). "To investigate whether our results could have potential clinical implications, we explored the possible impact of SMOC2 on vascular calcification, which is a common complication of frequent vascular diseases such as atherosclerosis, predicting cardiovascular morbidity and mortality." (PMID 29897942, 2018).
atrial fibrillation (1 paper, 2024). A disorder characterized by an electrocardiographic finding of a supraventricular arrhythmia characterized by the replacement of consistent P waves by rapid oscillations or fibrillatory waves that vary in size, shape and timing and are accompanied by an irregular ventricular response. "MSC-Exo was also effective in atrial fibrillation (AF) in a study that demonstrated miR-148a in the MSC-Exo played a vital role in inhibiting SMOC2 to provide cardioprotective effects." (PMID 39769256, 2024).
autoimmune disease (1 paper, 2015). A disorder resulting from loss of function or tissue destruction of an organ or multiple organs, arising from humoral or cellular immune responses of the individual to their own tissue constituents. "Genome-Wide Association Study (GWAS) has indicated that SMOC2 is a risky gene locus for generalized vitiligo, which occurs concomitantly with RA and other autoimmune diseases." (PMID 26359667, 2015).
brain tumors (1 paper, 2022). "SMOC1, a SPARC-related ligand overexpressed in brain tumors, recovered BST2, IGSF23, and SMOC2 as the highest-ranking hits." (PMID 36178190, 2022).
calcification (1 paper, 2018). Process by which organic tissue becomes hardened by the physiologic deposit of calcium salts. "We propose a possible role for SMOC2 to prevent calcification disorders." (PMID 29897942, 2018).
cardiomyopathy (1 paper, 2017). A disease of the heart muscle or myocardium proper. "Analysis of pathways that were dysregulated across cardiomyopathy phenotypes identified shared genes that were associated with extracellular matrix remodeling and thus likely fibrosis (THY1, CILP, OGN, THBS4, ASPN, HAPLN1,and SMOC2), as well as calcium (ADIPOQ, ASPN, THBS4, STAT4, and SMOC2)." (PMID 28098235, 2017).
cartilage disease (1 paper, 2021). Softening and degeneration of the CARTILAGE. "Thus, our findings reveal that the Bmp2–Runx2–Smoc1/Smoc2 axis plays an important role in bone formation; it may offer novel and effective therapeutic strategies associated with various bone and cartilage diseases." (PMID 34667264, 2021).
chronic periodontitis (1 paper, 2020). A chronic inflammatory process that affects the tissues that surround and support the teeth. "To assess such possible defects, we performed μCT imaging on 1-year old mice, and found that ~ 40% of Smoc2−/− mutants displayed spontaneous chronic periodontitis due to aging (n = 10)." (PMID 32908163, 2020). "With aging, Smoc2−/− mutant mice exhibit spontaneous alveolar bone deterioration and maxillary molar root resorption mimicking age-dependent dental and periodontal changes such as periodontal disease encountered in elderly human patients." (PMID 32908163, 2020).
colitis (1 paper, 2023). Inflammation of the colon. "Indeed, the expression of Smoc2 is described to be strongly increase during colitis." (PMID 37996842, 2023).
dwarfism (1 paper, 2021). "Because we observed dwarfism and shortened long bones in Smoc1 and Smoc2 DKO mice, we investigated the roles of Smoc1 and Smoc2 in endochondral bone formation." (PMID 34667264, 2021).